POSTN (periostin)
Diseases named in the same sentence as POSTN in open-access papers (continued):
Sharing a sentence is not in itself a finding about the gene and the disease.
breast carcinoma (continued). "POSTN promotes a stem cell-like trait in breast cancer cells and contributes a microenvironmental niche supportive of the maintenance of breast cancer stem cells." (PMID 28526827, 2017). "For example, secretion of TGF-β2/TGF-β3 from breast cancer cells that disseminated to the lung has been shown to induce stromal fibroblast expression of periostin (POSTN), which is a component of the ECM." (PMID 33959299, 2017). "A prospective study involving a large number of cases is necessary in order to overcome these limitations and evaluate the predictive and prognostic value of periostin expression in breast carcinoma." (PMID 29161296, 2017). "Overexpression of periostin in human breast cancer cells leads to a significant enhancement of angiogenesis." (PMID 29161296, 2017). "Human MDA-MB-231 breast cancer cells engineered to overexpress periostin showed a phenotype of accelerated angiogenesis as xenografts in immunocompromised animals." (PMID 29161296, 2017). "Another component of the ECM, periostin (POSTN), is induced in breast cancer metastases, where it has been found to play a critical role in their development through the maintenance of CSCs." (PMID 28974015, 2017). "Few studies on human breast cancer have revealed that periostin expression is considerably higher in cancer tissues than in normal tissues and is considered as tumor-enhancing factor." (PMID 29161296, 2017). "Stroma-derived POSTN plays a critical role in the crosstalk between breast cancer stem cells and their niche to determine the success of metastatic colonization." (PMID 28526827, 2017). "Previous studies have shown that periostin is highly expressed in various types of malignant tumor including non-small cell lung cancer, breast cancer, colon cancer, and epithelial ovarian cancer." (PMID 29163770, 2017). "Ectopic overexpression of POSTN or recombinant POSTN can induce multipotent stem cell-like properties in human mammary epithelial cells and breast cancer cells." (PMID 26556874, 2016). "Summarizing, we confirmed by western blot analysis, the differential proteomic content of 67NR and 4T1 exosomes, identifying β-catenin, integrin α2 and β1, periostin and E-Cadherin, as putative markers of metastasis in mouse mammary carcinoma cell lines." (PMID 27589561, 2016). "Periostin is a secreted protein with a significant role in the adhesion of osteoblasts and has been found to be upregulated in several cancer types including breast cancer." (PMID 27589561, 2016). "In summary, periostin was found to be enriched in mouse and human breast cancer exosomes compared to their parental cells and in exosomes from patients with lymph node metastasis compared to exosomes from patients with localized disease." (PMID 27589561, 2016). "Stromal expression of POSTN was also correlated with poor survival and bone metastasis in breast cancer." (PMID 26716408, 2016). "Concerning the validation of putative biomarkers in breast cancer patient samples, periostin was detected in higher levels in more samples from exosomes with metastatic breast cancer than in exosomes with non-metastatic breast cancer." (PMID 27589561, 2016). "Periostin is a secreted protein involved in the adhesion of osteoblasts and it is upregulated in several cancer types (ovarian, non-small cell lung cancer and breast cancer)." (PMID 27589561, 2016). "Periostin has an important role in breast cancer as it maintains cancer stem cell properties and a potential drug target where periostin's interaction with integrins is disrupted." (PMID 27589561, 2016). "We identified periostin as a protein that is enriched in exosomes secreted by metastatic cells and validated its presence in a pilot cohort of breast cancer patient samples with localized disease or lymph node (LN) metastasis." (PMID 27589561, 2016). "Combined evaluation of CTHRC1 and periostin can serve as a potential marker for breast cancer bone metastasis." (PMID 26023718, 2015).
breast carcinoma (continued). "In a mouse breast cancer model, it was recently shown that stromal POSTN in the lung promotes metastatic colonization by interacting with breast cancer stem cells and serving as a metastatic niche." (PMID 26083413, 2015). "Metastasising breast cancer cells induce periostin secretion in the cancer stem cell niche and require continued stromal periostin expression for cancer stem cell maintenance." (PMID 25345775, 2015). "Periostin overexpression is observed in various types of cancer, including thymoma, non-small cell lung carcinoma, breast cancer, pancreatic ductal adenocarcinoma, and in ascites from ovarian cancer patients." (PMID 24146092, 2014). "In this study, we characterized the interaction between cellular decorin and periostin not only in phyllodes tumors but also in BT-20 breast cancer cells." (PMID 25400079, 2014). "To further understand the roles of POSTN in breast cancer progression, we characterised the effects of POSTN on the stemness and multilineage differentiation potentials and tumorigenicity of human mammary epithelial cells and breast cancer cells (BCCs)." (PMID 24009721, 2013). "Our results provide a new view for understanding the multifaceted roles of POSTN in breast cancer progression." (PMID 24009721, 2013). "POSTN plays a critical role in the crosstalk between murine breast cancer stem cells (CSCs) and their niche to permit metastatic colonization." (PMID 24009721, 2013). "A recent report demonstrated that stromal POSTN is a key limiting factor that regulates the lung metastasis of mouse breast tumors and that POSTN can augment Wnt signalling in mouse breast cancer stem cells (CSCs)." (PMID 24009721, 2013). "Here we demonstrate that POSTN promotes a stem cell-like trait and a mesenchymal phenotype in human mammary epithelial cells and breast cancer cells." (PMID 24009721, 2013). "Periostin is overexpressed in various types of human cancer tissues, including ovarian cancer, cholangiocarcinoma, breast cancer, colon cancer, esophageal cancer, head and neck cancer, and pancreatic ductal adenocarcinoma (ADC)." (PMID 24273600, 2013). "Taken together, these findings demonstrated that CAF-produced POSTN in the lung drives metastatic colonisation of disseminated breast carcinoma cells via induction of Wnt signalling and thus the CSC trait." (PMID 24216702, 2013). "The outcome demonstrated that periostin plays an important role in breast cancer’s resistance to chemotherapy." (PMID 23056395, 2012). "Correlations between periostin expression and chemotherapeutic resistance in breast cancers (n = 135; n(%))." (PMID 23056395, 2012). "We further studied the relationship among age, tumor size, histological grade, histological type, molecular type, CSC ratio, periostin expression and chemotherapeutic sensitivity in 135 neoadjuvant chemotherapy breast cancers." (PMID 23056395, 2012). "Immunohistochemical examination showed that periostin was located in the cytoplasm and membrane of the breast cancers." (PMID 23056395, 2012). "Currently, the expression status of periostin protein in breast cancer and its relationship to the biological behavior of the disease are still unclear." (PMID 23056395, 2012). "It was also observed that periostin protein was expressed significantly higher in breast cancer tissues compared to paracancerous tissue and atypical hyperplasia tissues (30.76% vs 7.92% vs 5.99%, respectively)." (PMID 23056395, 2012). "We also investigated the relationship between periostin expression and the biological behavior of breast cancer stem cells and the clinicopathological characteristics of breast cancer." (PMID 23056395, 2012). "We investigated the expression status of periostin in breast cancer stem cells and its clinical implications in order to lay a foundation for managing breast cancer." (PMID 23056395, 2012). "Currently, the periostin expression status in breast cancer stem cells (CSC) and clinical implications for breast cancer are also unclear." (PMID 23056395, 2012).
breast carcinoma (continued). "In the present study, we try to sort and identify breast cancer stem cells investigate the expression status of periostin in those cells cells, and evaluate the clinical implications of periostin in breast cancer." (PMID 23056395, 2012). "No studies to date, however, have examined the relationship among periostin expression status and breast cancer CSC ratio, chemotherapy sensitivity, and the clinical implications of breast cancer." (PMID 23056395, 2012). "Up-regulation in the protein-coding gene POSTN (periostin) is correlated with metastasis in both melanoma and breast cancer." (PMID 21756334, 2011). "Recently, periostin was found to be overexpressed in various types of human cancers including non-small-cell lung cancer, breast cancer, ovarian cancer, colon cancer, head and neck cancer, pancreatic cancer, liver cancer and neuroblastoma." (PMID 21504578, 2011). "POSTN expression levels <5 were detected in 16/19 cancer cell lines whereas strong expression was detected in Hs578T breast cancer cell line and LB831 bladder carcinoma cell line." (PMID 18086302, 2007). "Expression of POSTN is reportedly a bone metastasis from breast cancer and is proposed as a prognostic marker in lung tumor invasion." (PMID 17411443, 2007). "In veterinary medicine, PDPN, similar to POSTN, has been recognised and described in some lesions such as mammary carcinoma, keratinising squamous cell carcinoma, melanoma or colon adenocarcinoma, however there is no information about its presence in testicular neoplasms." (PMID 41361308, 2025). "Similarly, in TAC-operated mice injected with breast cancer cells, increased cardiac and plasma levels of periostin and CTGF were observed, along with enhanced metastasis." (PMID 38279150, 2024). "Prior studies have shown that the aberrant expression of periostin may be related to the malignant progression of tumors; however, the biological function of periostin in the breast cancer and adipocyte microenvironment remains unclear." (PMID 37716956, 2023). "Furthermore, we investigated the pattern of POSTN mRNA expression in the breast cancer subclasses using UALCAN, which is a comprehensive, interactive web resource for analyzing cancer omics data." (PMID 37716956, 2023). "Periostin, a scaffold protein in the bone, can also activate Wnt/β-catenin signaling and contribute to dormancy exit and play a very similar role in breast cancer dormancy emergence." (PMID 37440925, 2023). "Another breast cancer study revealed that transforming growth factor-β could regulate POSTN production via PI3K/Akt pathway." (PMID 37919719, 2023). "It has been suggested that the use of such or similar aptamers may serve as a future therapeutic tool against those breast cancers that overexpress POSTN." (PMID 35268340, 2022). "A synthetic anti-POSTN peptide with binding affinity to POSTN has been shown to downregulate POSTN, thereafter reverse the drug resistance to doxorubicin in POSTN-overexpressed breast cancer cells." (PMID 35508298, 2022). "Though CTHRC1 and POSTN upregulation in breast cancer is associated with poor prognosis, no direct interaction between them is reported." (PMID 36190948, 2022). "In invasive ductal breast carcinoma (IDC), higher periostin expression levels in CAFs are associated with the grade of tumor cells and shorter overall survival, suggesting that periostin secreted by fibroblasts could be a marker in breast cancer progression." (PMID 36224629, 2022). "In addition, in breast cancer mouse model, tumor growth and metastasis were inhibited using benzyl-d(U)TP-modified DNA aptamers (PNDAs) targeted human periostin." (PMID 36224629, 2022). "Furthermore, to identify the roles of the POSTN C-terminal region in tumorigenesis, we performed immunostaining on sections isolated from patients with breast cancer using the monoclonal Ex17 antibody." (PMID 33919736, 2021).
breast carcinoma (continued). "Furthermore, the possibility of POSTN as a potential biomarker of the metastasis and chemotherapy resistance of breast cancer in a study of 1086 patients with breast cancer was noted." (PMID 33919736, 2021). "Additionally, periostin was shown to promote cell motility in ovarian cancer, while anti-periostin antibodies inhibited breast cancer progression and metastasis." (PMID 34200480, 2021). "Thus far, more than half of patients with breast cancer with lymph node metastasis have displayed the induction of stromal POSTN expression." (PMID 33919736, 2021). "In the case of the lung, another frequent metastatic site, several mechanisms have been implicated; Tank-binding kinase-1 (TBK1)-dependent promotion of proliferation of dormant breast cancer cells and upregulation of periostin (POSTN) expression, leading to Wnt signaling." (PMID 34064392, 2021). "PNDA-3 significantly inhibited the metastasis and growth of periostin-positive breast cancer." (PMID 34095130, 2021). "We hypothesized that the POSTN C-terminus plays an important role in breast cancer progression and metastasis." (PMID 33919736, 2021). "Periostin within the lung environment directly interacts with Wnt agonists Wnt1 and Wnt3a to potentiate Wnt signaling and promote the stemness characteristics of disseminated breast cancer cells." (PMID 33014869, 2020). "Moreover, breast cancer cells that infiltrate lung metastatic niches induced the expression of the matricellular protein periostin (POSTN) in endothelial cells." (PMID 33193295, 2020). "In breast cancer, periostin is expressed in invasive ductal carcinoma cells, and it might play a role in cancer progression." (PMID 32899501, 2020). "Importantly, in breast cancer metastasis models, periostin-mediated tumor initiation is specific to the lung microenvironment, since it does not affect the progression of primary breast tumors." (PMID 33014869, 2020). "In breast cancer patients who underwent surgery and radiation therapy, local recurrence-free survival, distant metastasis-free survival, and overall survival were significantly lower in the patients whose tumors expressed periostin." (PMID 32899501, 2020). "Whether ANRIL expression correlates with IL6, CCL2, and POSTN in breast tumors was also investigated to provide evidence of how ANRIL may contribute to inflammation in breast cancer." (PMID 31572679, 2019). "The subcellular localization of ANRIL and whether it correlates with IL6, CCL2, and POSTN expression, found in other conditions, in breast cancer is also unknown." (PMID 31572679, 2019). "The decrease of C-terminal intact periostin was namely shown to be a marker for osteolytic lesions in breast cancer bone metastasis and could be used to detect bone relapse in patients." (PMID 30897858, 2019). "However, in other studies POSTN in stromal cells was thought to be important in breast cancer progression." (PMID 31572679, 2019). "The relationship between serum POSTN levels and prognosis in breast cancer has also been studied." (PMID 29946533, 2018). "In this case, the higher levels of POSTN detected in CAF are associated with the malignancy grade of tumors, suggesting that POSTN secreted by CAFs could be a key element in breast cancer progression." (PMID 29946533, 2018). "Furthermore, periostin was found to support stem cell maintenance by facilitating Wnt signaling, thereby allowing breast cancer stem cells to initiate metastatic growth." (PMID 29903049, 2018). "Their studies revealed that high POSTN expression in these cells was associated with reduced relapse-free survival in basal-like type but not in breast cancers of the luminal type." (PMID 29946533, 2018). "Recent finding suggests that periostin may have a role in sprouting neovascular endothelial tips of disseminated tumor cells, promoting breast cancer cell outgrowth in a tumor-suppressive microenvironment." (PMID 29758011, 2018).
breast carcinoma (continued). "Periostin expression is increased in breast cancer tissues compared with normal tissues." (PMID 29161296, 2017). "Developing a further understanding of the cellular and molecular mechanisms by which periostin promotes tumor progression and identification of periostin functional modulators may allow the development of new strategies to treat breast cancer." (PMID 29161296, 2017). "Periostin was located in the cytoplasm and membrane of the breast cancer cells." (PMID 29161296, 2017). "A limited number of studies have investigated periostin expression in breast cancer." (PMID 29161296, 2017). "However, further studies are needed to clarify the role of periostin in breast cancer progression and metastasis." (PMID 29161296, 2017). "Identifying epithelial breast cancer cells as the unique source of periostin expression." (PMID 29161296, 2017). "POSTN supports the maintenance of breast cancer stem cells via POSTN-integrin signaling axis." (PMID 28526827, 2017). "Moreover, we observed a positive correlation of the mRNA levels between RUNX2 and BRGs (ITGBL1, SPARC and POSTN) in primary breast cancer tissues." (PMID 27806311, 2016). "Also, they reported that DNA aptamers targeting periostin can be used to inhibit breast cancer progression." (PMID 26023718, 2015). "Therefore, periostin qualifies as a tumor marker in the clinic, especially for advanced breast cancer." (PMID 26539408, 2015). "By combining the breast cancer model with periostin null mice, the authors could reveal that stromal periostin supports the survival and proliferation of cancer stem cells (CSCs, CD90+, and CD24+) through the activation of WNT signaling." (PMID 26539408, 2015). "This may have important implications for the treatment of breast cancers involving the therapeutic targeting of periostin or Notch signaling." (PMID 25592291, 2015). "PNDA-3 specifically antagonized periostin-induced adhesion and invasion of breast cancer cells." (PMID 26539408, 2015). "Additionally, by immunoprecipitation and mass spectrometry, we confirmed that decorin forms a complex with periostin in both phyllodes tumors and BT-20 breast cancer cells." (PMID 25400079, 2014). "Periostin-overexpressing human mammary epithelial cells acquire part of the multi-lineage differentiation potentials of mesenchymal stem cells and promote tumor growth and metastasis of human breast cancer cell line." (PMID 24146092, 2014). "Recent findings also suggest that periostin may have a role in sprouting neovascular endothelial tips of disseminated tumor cells, promoting breast cancer cell outgrowth in a tumor-suppressive microenvironment." (PMID 24146092, 2014). "Moreover, tenascin-C and periostin are both expressed in the hair follicle stem cell niche in murine skin and are crucial for metastatic breast cancer stem cells colonizing the lung." (PMID 25301723, 2014). "Our results reveal the molecular details of the periostin–decorin complex in both phyllodes tumor tissues and breast cancer cells; this interaction may represent a novel target for anti-cancer therapy." (PMID 25400079, 2014). "POSTN significantly promotes angiogenesis in human colon and breast cancers." (PMID 24009721, 2013). "POSTN also plays a role in human breast cancer progression by inducing angiogenesis." (PMID 24009721, 2013). "Increased POSTN serum levels are found in human breast cancer patients with bone metastases." (PMID 24009721, 2013). "In total, 334 (30.76%) of the 1,086 breast cancer cases showed high periostin expression." (PMID 23056395, 2012). "Periostin may also play a role in breast cancer oncogenesis and may be a potential biomarker for metastasis and chemotherapy resistance of breast cancer." (PMID 23056395, 2012). "Furthermore, studies that have addressed the relationship between periostin and chemotherapy sensitivity and prognosis of breast cancer are still sparse." (PMID 23056395, 2012).